RIMKLA (ribosomal modification protein rimK like family member A)
Description:
Catalyzes the synthesis of N-acetyl-L-aspartyl-L-glutamate (NAAG) and N-acetyl-L-aspartyl-L-glutamyl-L-glutamate.
Synonyms: NAAGS; FAM80A; MGC47816; RP11-157D18.1; NAAGS-II; NAAGS2
Tractability: PROTAC: ubiquitination databases record sites on it.
Target class: Enzyme; Ligase
Gene: Protein-coding gene on chromosome 1 (42,380,792 to 42,424,232, forward strand). Ensembl gene ENSG00000177181.
Subcellular location: Cytoplasm
Subcellular location (Human Protein Atlas): Nucleoli fibrillar center
Pathways (Reactome):
Metabolism: Glutamate and glutamine metabolism
Gene Ontology:
Molecular function: protein binding; N-acetyl-L-aspartate-L-glutamate ligase activity; ATP binding; metal ion binding
Biological process: L-amino acid metabolic process; L-glutamate catabolic process
Cellular component: cytoplasm; cytosol
Genetic constraint (gnomAD): Loss-of-function variants: 10 observed, 22.34 expected, observed/expected ratio (o/e) 0.45, 90% interval 0.28 to 0.76. The upper end of that interval is the gene's LOEUF score, 0.76, which puts it in group 3 of 6, group 1 being the genes least tolerant of losing a copy. Missense variants: 303 observed, 415.64 expected, observed/expected ratio (o/e) 0.73, 90% interval 0.66 to 0.8. Synonymous variants: 132 observed, 167.11 expected, observed/expected ratio (o/e) 0.79, 90% interval 0.69 to 0.91.
Homologues: Orthologues: chimpanzee RIMKLA (100% identical), macaque RIMKLA (99% identical), dog RIMKLA (97% identical), guinea pig RIMKLA (94% identical), pig RIMKLA (93% identical), mouse Rimkla (87% identical), rat Rimkla (87% identical), rabbit RIMKLA (86% identical), zebrafish rimkla (68% identical), tropical clawed frog rimkla (68% identical). Paralogues in human: RIMKLB (67% identical).
Diseases named in the same sentence as RIMKLA in open-access papers:
RIMKLA is named in the same sentence as 8 diseases in open-access papers, as found by Europe PMC text mining. Sharing a sentence is not in itself a finding about the gene and the disease. The quoted sentences say what the papers report.
Hyperglycemia (1 paper, 2024). An increased concentration of glucose in the blood. "Hepatic RIMKLA overexpression ameliorated steatosis and hyperglycemia in obese mice." (PMID 39117631, 2024).
Hyperinsulinemia (1 paper, 2024). An increased concentration of insulin in the blood. "Under obese condition, hyperlipidemia and hyperinsulinemia repress RIMKLA expression to inhibit BHMT1 activity, finally causing HHcy." (PMID 39117631, 2024). "Under obese condition, hyperlipidemia and hyperinsulinemia repress RIMKLA to impair BHMT1 activity and elevate Hcy level, which activates AP1 to induce the transcriptions of FASn and CD36, stimulating de novo lipid synthesis and uptake." (PMID 39117631, 2024).
tumor (2 papers, 2025). "Immunohistochemical database analysis reveals that EIF4EBP1, RIMKLA, and BIRC5 are highly expressed in tumour tissues, while the PCK1, PLG, PEBP1, and CAT show a lower expression in tumour samples." (PMID 40591061, 2025). "The hub node in PRAD and adjacent normal prostate tissues was shown in, RIMKLA, TPD52, and SEPTIN3 were highly expressed in PRAD, while other genes were low-expressed in tumor tissues in." (PMID 40341647, 2025). "The results revealed that EIF4EBP1, RIMKLA, and BIRC5 upregulated in tumor tissues, while other genes downregulated in normal tissues, which is consistent with the results in TCGA-KIRC datasets." (PMID 40591061, 2025).
metabolic disorders (1 paper, 2024). "The result revealed a stepwise decrease of RIMKLA expressions with the progression of metabolic disorders." (PMID 39117631, 2024).
RIMKLA also shares sentences with these, for which no sentence is quoted: Hepatic steatosis (1 paper); hyperlipidemia (1); Insulin resistance (1); steatosis (1).